SPP1 (secreted phosphoprotein 1)
Diseases named in the same sentence as SPP1 in open-access papers (continued):
Sharing a sentence is not in itself a finding about the gene and the disease.
tumor (continued). "Previous studies have well documented diverse aggressive phenotypes induced by OPN (SPP1) in HCC, including tumor growth, metastasis, epithelial-mesenchymal transition, stemness, drug resistance, immunosuppression, and etc.." (PMID 32576292, 2020). "The results showed that YBX1 or G3BP1 overexpression significantly (p < 0.01) promoted tumor cell migration and invasion in RCC ACHN cells, while SPP1 depletion strongly attenuated the effect of YBX1 or G3BP1 induced RCC cells migration and invasion." (PMID 31481087, 2019). "Previously, in young mice, we have shown that tumour blood perfusion and tumour OPN level, as well as the Spp1 mRNA level in lung tissue, were stimulated by treatment with calcitriol and its analogues, and there was increased metastatic potential of 4T1 cells." (PMID 31595196, 2019). "The genes that were overexpressed in both senescent thyrocytes and at least one tumor cell line included genes coding for: the chemokines CCL3 and CCL-4, the cytokine IL-1β, the matrix-related protein SPP1, and the enzyme PTGS2." (PMID 31113465, 2019). "Subsequently, we will develop a sensitive technique to detect the presence of SPP1 and LCAT in cell-free circulating tumor DNA (ctDNA), which will not only benefit patients who undergo surgery but will also help to screen patients with HCC." (PMID 31695766, 2019). "Since an effective tumor marker should be instinctively higher in cancer patients, we chose GPC3 and SPP1 for further analysis." (PMID 31635078, 2019). "OPN (SPP1) is an interesting protein that is involved in inflammatory processes and it resulted higher in urine samples of tumor patients." (PMID 30813269, 2019). "Osteopontin (OPN; SPP1) and two proteins of the serpin family, such as SERPINA1 and SERPINA3, were those with higher expression in the P3 subtype compared to the rest of tumours." (PMID 31560832, 2019). "Only SPP1 and MMP12 were also present in the whole tumour signature, suggesting that these targets are also abundantly expressed in other cell types, in addition to ECs." (PMID 28487489, 2017). "FN1, SPP1, CXCL12 and vitronectin (VTN) are known to promote the survival and migration of tumor cells." (PMID 27329720, 2016). "As was consistent with the qRT-PCR results, SPP1, COL1A1 and NT5E proteins were up-regulated, while the expression of HTRA1 and ANGPT1 were down-regulated in the tumor compared with ANPT groups (n = 29)." (PMID 27690016, 2016). "Collectively, we suggest that the FN1/SPP1-ITGAV pathway plays an important role in the chemotaxis of tumor cell to fibrotic lungs and in the apoptosis resistance of seeding tumor cells in the lungs." (PMID 27329720, 2016). "We developed a four-gene expression signature (HIST1H2BG, SPP1, ELF3 and PCA3) with a sensitivity of 77 % and a specificity of 67 % (AUC = 0.763) for discriminating between tumor and control urines." (PMID 26856686, 2016). "Second, both CM-FL and CM-FLF chemoattracted tumor cells and decreased the apoptosis of tumor cells, while silencing FN1 or SPP1 in fibroblasts attenuated the CM-FLF-promoted apoptosis resistance and chemotaxis of tumor cells." (PMID 27329720, 2016). "Taken together, we disclosed the role of chemotaxis and apoptosis in the fibrotic microenvironment-enhanced seeding of tumor cells and identified the fibroblast-derived FN1 and SPP1 as the central mediators in these processes." (PMID 27329720, 2016). "This would help to explore further the relationship with NF1 of not only SPP1 but the other identified statistically significant genes, which are differentially expressed between benign and malignant NF1 tumours." (PMID 25884485, 2015). "We showed that DEX inhibited CXCL13 production by epithelial cells and SPP1 production by TAMs, inhibited the EMT, reduced the tumor burden and prolonged the life span of the mice, revealing a new mechanism for this existing drug." (PMID 26565418, 2015).
tumor (continued). "Gelatinase activity was one major GO annotation of these eight genes (CA7, SPIB, GUCA2B, AQP8, IL6R, SPP1, TCN1, and CWH4) and is related to tumor progress and metastasis." (PMID 24959000, 2014). "SPP1 is reported to interact with CD44 receptor and is thought to exert pro-metastatic effects leading to tumor progression by regulating the cell signaling events." (PMID 23166660, 2012). "Five target genes were significantly overexpressed in the tumour samples compared with normal bladder tissue: FOXM1, IGF2, OSF2, and H19, which promote cell proliferation and growth, and SPP1, which is involved in extracellular matrix interactions." (PMID 22361633, 2012). "SPP1 is a ligand of CD44 that binds to αV-containing integrins and is important in malignant cell attachment and tumor invasion." (PMID 21333016, 2011). "CFD/Adipsin median levels were found to be lower in tumours compared to the levels in PN and AN (p = 0.0324), while CXCL5/ENA78, CCL20/MIP-3α, IGFBP3, SPP1/OPN and TIMP1 were increased in PN and tumours relative to AN, with higher levels seen in tumours." (PMID 21092330, 2010). "Secreted phosphoprotein 1 (SPP1) is also known as OPN and its abnormal activation can stimulate tumor growth, invasion, angiogenesis, and immune suppression, with wide-ranging effects on cell proliferation, apoptosis, differentiation, and migration." (PMID 21080944, 2010). "Many of the genes identified during promotion (e.g. Ereg, Hbegf, and Spp1) can signal through EGFR or are involved in EGFR signaling events which can then lead to cell growth and eventual tumor development." (PMID 19925653, 2009). "Notable exceptions were genes such as SPP1, HOXA10 and MMP14, for which the greatest differential increase in expression was at the comparative interface between thin and I.M. thickness tumor samples." (PMID 18442402, 2008). "Subsequent analysis utilizing the CellPhoneDB-secreted ligand‒receptor database revealed that tumor cells with high PSMD1 expression predominantly employ ligands such as MIF, MDK, and SPP1 as signaling molecules to communicate with immune cells within the microenvironment." (PMID 41535254, 2026). "Among these, the CXCL9+SPP1- subpopulation exhibited macrophages with anti-tumor features, whereas the CXCL9-SPP1+ subpopulation showed macrophages with pro-tumor features." (PMID 42079623, 2026). "This may be related to the interaction between secreted SPP1 and CD44 on the surface of tumor cells, which activates the PDE3B pathway." (PMID 41056019, 2026). "Within the intricate tumor ecosystem, the differentiation of macrophages into a specific SPP1-expressing phenotype is not an autonomous process." (PMID 41425545, 2025). "For EGFRvIII(+) GBM patient single-cell data, the pattern analysis results showed that in the outgoing pattern analysis, tumor cells dominated Pattern3, with the MDK signaling pathway being the most active in Pattern3, followed by the PTN and SPP1 signaling pathways." (PMID 40527884, 2025). "Additionally, spatial mapping identified immunosuppressive barriers at tumour boundaries, formed by COL11A1+ CAFs and SPP1+ macrophages, which physically block T cell infiltration." (PMID 40677104, 2025). "Therefore, experimental designs should integrate spatial and multi-omics pharmacodynamic indicators, such as the reduction of TAM-tumor-CAF neighbor clusters, decreased TREM2 or SPP1 TAM load, and normalization of CCL2, IL10, and TGFB." (PMID 41488638, 2025). "SPP1 and TGFA further enhance proliferation and tumor growth." (PMID 41303451, 2025). "Moreover, interactions between SPP1+ macrophages and CAFs exacerbate ECM stiffening, providing a physical scaffold that supports tumor growth and metastasis." (PMID 41391064, 2025).
tumor (continued). "In vivo experiments: Utilizing humanized or immunocompetent IBC mouse models to evaluate the effects of SPP1 knockout or anti-SPP1 neutralizing antibodies, as well as depletion of pDCs or inhibition of their GZMB activity, on tumor growth, metastasis, and treatment response." (PMID 41567210, 2025). "High SPP1 expression in the TME is strongly correlated with increased macrophage infiltration, suggesting that SPP1 plays a direct role in guiding macrophage migration to tumor sites." (PMID 41391064, 2025). "Notably, two of the 11 ICD-related genes that constitute the prognostic signature, SPP1 and SLC11A1, were exclusively expressed in macrophages within tumor samples." (PMID 40740776, 2025). "Additionally, studies have demonstrated that SPP1 macrophages can bind to CD44 on the surface of T cells, thereby suppressing their anti-tumor function." (PMID 40474968, 2025). "By inhibiting key signaling molecules such as SPP1 and CXCL12 or even by interfering with exosome release, researchers hope to disrupt the paracrine communication that fosters antiangiogenic TKI resistance and promotes tumor survival." (PMID 40507341, 2025). "Furthermore, we identified SPP1+ macrophages as a critical component of the TME in LM, where they interacted with LEMS to enhance tumor cell migration and invasion." (PMID 41176774, 2025). "In summary, YBX1 promotes tumor progression through its transcription factor activity, exerting its effects via various downstream targets such as MUC1, CDC25a, NANOG, Kindlin-2, G3BP1, AURKA, SPP1, the EGFR-RAS-MAPK axis, CORO1C, among others, depending on the specific tumor type." (PMID 40799245, 2025). "AR+/TREM2+/SPP1+ TAM fraction; TAM–tumor proximity scores; APOE–TREM2 pathway activity." (PMID 41488638, 2025). "Additionally, tumor signaling was seen to affect profibrotic polarization in the liver, enriching the SPP1 interactions and contributing to CD8 + T cell dysfunction in the tumor microenvironment." (PMID 40335453, 2025). "This suggested that high expression of CDC20, LPCAT1, and SPP1, as well as low expression of PON1, may affect the immune escape and cell metabolism of tumor cells, reducing TACE treatment sensitivity." (PMID 40404896, 2025). "High-dimensional multi-omics analysis of patient samples further revealed an elevated frequency of exhausted tumor-reactive CD8+ T cells and enhanced interactions between these T cells and SPP1+ macrophages, particularly within profibrotic, α-SMA-rich regions of the liver." (PMID 41425545, 2025). "Additionally, SPP1+ TAM abundance was markedly elevated in patients with advanced-stage tumors, suggesting a role in tumor progression." (PMID 40725473, 2025). "SPP1+ and CXCL5+ macrophages, primarily enriched in tumor tissues, were designated as TAMs." (PMID 40191203, 2025). "This renders tumor blood supply more resistant to TACE embolic blockade; meanwhile, SPP1 activates PI3K/Akt pathways in endothelial cells, upregulating matrix metalloproteinase expression and facilitating vascular wall remodeling, establishing channels for tumor cell invasion and metastasis." (PMID 41450464, 2025). "We then selected fibroblast or SPP1+ TAMs-CAFs spots, accordingly, ensuring that these spots were within a distance no greater than 2.5 times that of the hepatocyte or tumor cell spots." (PMID 40230843, 2025). "SPP1 was highly expressed in the tumor regions, unlike other macrophage markers that were only highly expressed in the fibroblast region." (PMID 40092488, 2025). "In our study, the interaction between LEMS and SPP1+ macrophages, mediated by specific receptor‐ligand pairs such as MDK‐SDC4, FN1‐CD44, and COL6A1‐CD44, suggests a cooperative relationship that enhances tumor cell migration and invasion." (PMID 41176774, 2025). "Additionally, LILRB4 + MM cells communicate with monocytes through the SPP1/CD44 axis, which likely contributes to the regulation of the monocyte–macrophage system within the tumor microenvironment." (PMID 41417876, 2025).
tumor (continued). "Furthermore, inflammatory macrophages, such as SPP1+ and CCL20+ macrophages, exhibited increased cell-cell communication with tumor cells in the high GLMscore group, potentially mediated by the PPIA-BSG signaling pathway." (PMID 40443528, 2025). "Notably, the crosstalk between SPP1+ macrophages and FAP+ CAFs was found to promote tumor progression." (PMID 41425545, 2025). "In head and neck cancer models, targeting SPP1+ macrophage derived cytokines, particularly TNF-α and IL-1β with the inhibitor significantly impaired tumor cell proliferation and migration in vitro and reduced tumor growth in vivo." (PMID 41425545, 2025). "More importantly, Spp1-cKO mice exhibited significantly reduced tumor growth and better ICI treatment efficacy based on tumor volume, paralleled by an increase in tumor-infiltrating CD4+/CD8+ T cells and DNT cells." (PMID 40312419, 2025). "This included Spp1, which was strongly repressed by DMXAA in cocultured tumor cells but unchanged in DMXAA treated monocultures, demonstrating that the effect of DMXAA on CAFs regulates Spp1 expression in tumor cells." (PMID 40215177, 2025). "Moreover, the ligand-receptor signaling differences between HCC and normal samples showed that pathways such as SPP1, LAMININ and VTN were more prevalent in the HCC microenvironment, suggesting enhanced tumor growth, invasion, and immune evasion." (PMID 40612108, 2025). "Additionally, through binding with CD44 and integrins, SPP1 enhances ECM remodeling, increases tumor stroma stiffness, and supports immune evasion." (PMID 41391064, 2025). "Notably, SPP1+ macrophages interacted with FAP-positive CAFs, contributing to the establishment of a hypoxic tumor microenvironment, which is known to promote tumor progression and resistance to therapy." (PMID 40599798, 2025). "Conversely, the expression of SPP1 was not significantly different between tumor tissues and normal tissues, as indicated by the non-significant p-value in the RT-qPCR analysis." (PMID 40809844, 2025). "Although not statistically significant, both TAM(C1Q) and TAM(SPP1) exhibited an increasing trend with tumour progression." (PMID 40318012, 2025). "Figure P: The expression of SPP1 was not upregulated in the four tumor cell lines compared to that in the HOK cell line." (PMID 39744569, 2025). "Our results demonstrated that SPP1 is mainly produced by cancer cells and is significantly increased in the plasma of polymorphonuclear myeloid‐derived suppressor cell (PMN‐MDSC)‐dominant tumor‐bearing mice." (PMID 39939411, 2025). "The interactions between SPP1+ macrophages and FAP+ fibroblasts could be a prospective point for anti-tumor progression and metastasis." (PMID 40438108, 2025). "Recently, it has been reported that the interaction between SPP1+ Mac and FAP+ fibroblasts may promote the formation of demyelinated regions in the tumor microenvironment by remodeling the ECM." (PMID 40001138, 2025). "The binding of SPP1 to CD44 on T cells and tumor cells may help maintain an immunosuppressive microenvironment that supports tumor survival and growth." (PMID 41391064, 2025). "Supporting these findings, our results showed that SPP1 expression exhibited dynamic changes, with a sustained increase from non-tumor tissue to tumor border, and tumor core." (PMID 40901047, 2025). "Functionally, SPP1+ TAMs play a central role in promoting tumor cell epithelial-mesenchymal transition (EMT), angiogenesis, intravasation, metastasis, and immunosuppression through the secretion of factors including SPP1, CCL18, CXCL8, TNF-α, and IL-1β." (PMID 41459510, 2025). "Moreover, studies suggested that SPP1 in GBM sustains GBM survival and stimulates tumor angiogenesis by upregulating the expression of PSMA in endothelial cells through the transcription factor HIFα." (PMID 40375334, 2025).
tumor (continued). "Different subsets of immunosuppressive TAMs (SPP1-C1Qa/b, proliferating, Nos2 glycolytic and OXPHOS TAMs) exhibited high expression of Trem2, Axl, Tim3 and Arg1, known markers of a pro-tumor phenotype, and were proportionally decreased in response to ACTM-838 treatment (except OXPHOS TAMs)." (PMID 41048107, 2025). "Targeting and blocking the SPP1/CD44 pathway has been shown to restore T cell function and inhibit tumor growth, suggesting that this pathway may serve as a promising therapeutic target for HCC." (PMID 40474968, 2025). "These methods allow for a more granular understanding of gene expression within individual cell types in the tumor and could clarify whether COL3A1, PLAU, and SPP1 are differentially expressed across various cell types within the same tumor." (PMID 41465316, 2025). "However, if exogenous human SPP1 protein is added, the expression of proliferation‐related genes (UBE2C, E2F1) in the co‐cultured tumor cells increases." (PMID 39716897, 2024). "Even though anti-PD-1 treatment decreased the percentage of cancer cells in subcluster “Autophagy” in DRG2-depleted tumors, this did not lead to inhibition of the tumor progression, possibly because of expansion of the subcluster “Spp1 + ” population." (PMID 38802348, 2024). "Thus far, we have shown a correlation between profibrotic proteins in the primary CRC tumor and the expression of FN1 and SPP1 in the metastatic intrahepatic tumor." (PMID 39372792, 2024). "Taken together, FAP+ fibroblasts and SPP1+ macrophages coordinated to remodel ECM and promoted connective tissue proliferation, preventing the infiltration of lymphocytes into the tumor core and thereby reducing the efficacy of programmed death-ligand 1 (PD-L1) blockade immunotherapy." (PMID 39858416, 2024). "Furthermore, the presence of SPP1+ macrophages in the triad structure, alongside endothelial and POSTN+ FAP+ CAFs, suggests a role in promoting tumor development through pro‐angiogenic properties and activation of CD44 in tumor cells." (PMID 39716897, 2024). "Upregulation of BRMS1 in microglia may lead to M2 macrophage polarization, activate the PI3K/AKT signaling pathway through SPP1/CD44-mediated cell interactions, inhibit tumor cell apoptosis, and promote tumor proliferation and invasion." (PMID 39143438, 2024). "Once cancer cells had spread to the regions of cluster 3, interactions between SPP1+ macrophages and fibroblasts were observed, which may aid in avoiding cytotoxicity by immune cells and, as a result, EMT in tumor cells themselves." (PMID 39639005, 2024). "Moreover, signaling pathways such as SPP1, APRIL (TNFSF13), and IL4 were notably enhanced in the tumor region." (PMID 38938448, 2024). "Moreover, SPP1 + Mac-derived TNF-α and IL-1β promoted the expression of OPN in both tumor cells and other adjacent macrophages through different signaling pathways." (PMID 39726047, 2024). "In addition to the L–Rs involved in the MIF pathway, there were many other L–Rs in the PT microenvironment to promote tumor progression, such as SPP1-CD44 of SPP1 pathway." (PMID 38414027, 2024). "More importantly, within SPP1 + macrophages, SIRPα positive cells exhibited enhanced phagocytic potential and were in closer proximity to both tumor cells and CD8 + T cells compared to SIRPα negative cells." (PMID 39696410, 2024). "Notably, among the hub genes, up-regulated SPP1 and down-regulated KRT78 expression significantly correlated with tumor grade, individual cancer stages, and poor survival in patients with HNSCC." (PMID 39596132, 2024). "Inhibiting SPP1 + Mac-derived TNF-α and IL-1β suppressed tumor growth both in vivo and in vitro." (PMID 39726047, 2024). "Notably, secretory ligands SPP1 and NAMPT in CXCL8hiIL1Bhi macrophages played a role in tumorogenesis by sending signals to receptors on stromal and tumor cells." (PMID 39229264, 2024).